ADAMTS7 (ADAM metallopeptidase with thrombospondin type 1 motif 7)
Diseases named in the same sentence as ADAMTS7 in open-access papers (continued):
Sharing a sentence is not in itself a finding about the gene and the disease.
osteoarthritis (15 papers, 2014 to 2025). A noninflammatory degenerative joint disease occurring chiefly in older persons, characterized by degeneration of the articular cartilage, hypertrophy of bone at the margins and changes in the synovial membrane. "Upregulated DE genes were further enriched for targets of ZNF-507 transcription factor, which is predicted to interact with ADAMTS-7, a metallopeptidase previously associated with osteoarthritis." (PMID 35088088, 2022). "ADAMTS7 is also involved in the progression of osteoarthritis since it promotes the breakdown of cartilage oligomeric matrix protein (COMP)." (PMID 41296055, 2025). "For instance, ADAMTS7 significantly contributes to tissue remodeling and disease progression in osteoarthritis through the specific degradation of the extracellular matrix protein COMP44." (PMID 39781347, 2025). "Increased concentrations of TSP-5 fragments and ADAMTS7 were measured in the synovial fluid and in the serum of patients with rheumatoid arthritis and osteoarthritis." (PMID 36833435, 2023). "Cultured synovial fibroblasts from healthy individuals and patients with osteoarthritis can secrete ADAMTS-7." (PMID 29523183, 2018). "In the stage 4 ONFH group, which performed secondary osteoarthritis caused by ONFH, level of ADAMTS-7 was the highest among the stages." (PMID 25653475, 2015). "It was reported that ADAMTS-7 formed a positive feedback loop with TNF-α in the pathogenesis of osteoarthritis." (PMID 24876675, 2014). "For instance, ADAMTS-7 mRNA is found to be significantly increased in the cartilage of patients with rheumatoid arthritis (RA) and only slightly increased in the cartilage of patients with osteoarthritis (OA), whereas ADAMTS-12 mRNA is significantly increased in both OA and RA cartilage." (PMID 24876675, 2014). "The cited authors showed that ADAMTS group enzymes, namely ADAMTS7 and ADAMTS12, are overexpressed in cartilage and synovial membrane in osteoarthritis patients, contributing to COMP degradation." (PMID 36079004, 2022). "Overexpression of ADAMTS-7 gene promotes the breakdown of cartilage oligomeric matrix protein (COMP) matrix and accelerates the progression of both surgically induced osteoarthritis and collagen-induced arthritis." (PMID 26696755, 2015). "Additionally, acetyl-CoA orchestrates epigenetic modulation, affecting multiple cellular processes critical for osteoarthritis pathogenesis, including the transcriptional activation of MMP13 and ADAMTS7." (PMID 40425566, 2025). "The ADAMTS7 gene, also referred to as COMP-ADAMTSs due to its role in degrading cartilage oligomeric matrix protein (COMP), has been found to be significantly elevated in conditions such as osteoarthritis and rheumatoid arthritis." (PMID 40564318, 2025). "Similarly, RT-PCR with specific primers for human ADAMTS-7 showed that ADAMTS-7 mRNA level exhibits a parallel trend as the immunohistochemistry results, which is in line with ADAMTS-7 expression pattern in primary osteoarthritis." (PMID 25653475, 2015). "Moreover, ADAMTS-7 and tumor necrosis factor-α (TNF-α) form a positive feedback loop in osteoarthritis." (PMID 26696755, 2015).
acute myocardial infarction (8 papers, 2015 to 2024). Necrosis of the myocardium, as a result of interruption of the blood supply to the area. "The object of the study was to investigate the association between the rs3825807 polymorphism of ADAMTS7 and myocardial infarction among patients with type 2 diabetes mellitus in a Slovenian cohort." (PMID 36833435, 2023). "In a rat model, ADAMTS-7 was poorly expressed in myocardial cells 28 days after myocardial infarction." (PMID 39768861, 2024). "There is little expression of ADAMTS-7 in the myocardium rats 28 days after myocardial infarction." (PMID 29523183, 2018). "The study aimed to examine plasma ADAMTS-7 levels in patients with acute myocardial infarction (AMI) and the relationship between plasma ADAMTS-7 levels and heart function." (PMID 25885961, 2015).
rheumatoid arthritis (7 papers, 2014 to 2025). A chronic, systemic autoimmune disorder characterized by inflammation in the synovial membranes and articular surfaces. "Furthermore, the upregulation of ADAMTS-7 was also associated with the increased level of TNF-α in rheumatoid arthritis (RA) patients and patients with femoral neck fracture (FNF) and osteonecrosis of femoral head (ONFH) at different stages." (PMID 26696755, 2015). "The increased expression of ADAMTS-7 in the joint tissues of degenerative diseases, such as OA and rheumatoid arthritis (RA), patients is due to proinflammatory cytokines, including TNF-α." (PMID 25653475, 2015). "Moreover, elevated ADAMTS7 levels were found in rheumatoid arthritis patients." (PMID 35503474, 2022).
Arthritis (6 papers, 2015 to 2023). Inflammation of a joint. "For example, ADAMTS7 (rs3825807) encodes a metalloproteinase that has been associated with arthritis and also with the thickening of the neointima occurring in cardiovascular events." (PMID 28982122, 2017). "Collectively, the role of ADAMTS-7 in the pathogenesis of arthritis is associated with degradation of COMP and upregulation of inflammatory cytokines and other metalloproteinases." (PMID 26696755, 2015). "ADAMTS7 also plays a role in the association with arthritis and disc disease." (PMID 36833435, 2023). "In collagen-induced arthritis (CIA) mode, ADAMTS-7 transgenic mice were more susceptible to induction of CIA, and arthritic transgenic mice displayed significantly higher clinical and histological arthritis scores as compared with wild type mice." (PMID 26696755, 2015). "Animal results from surgically induced OA and collagen-induced arthritis models using ADAMTS-7 transgenic mice also supported the digestion of COMP by ADAMTS-7 in vivo." (PMID 26696755, 2015). "It has been proved that ADAMTS-7 plays an important role in the pathogenesis of OA; it directly associates with and degrades COMP in vitro, and the level of ADAMTS-7 is elevated in cartilage patients with arthritis." (PMID 25653475, 2015). "ADAMTS-7 has potential to serve as a therapeutic drug target in arthritis conditions." (PMID 26696755, 2015). "Thus, ADAMTS-7 expression was elevated during disease progression in surgically induced OA and collagen-induced arthritis model, and the increasing ADAMTS-7 upregulated the level of inflammatory cytokines including TNF-α." (PMID 26696755, 2015). "In addition, ADAMTS-12 also played a critical role in the pathogenesis of arthritis since ADAMTS-7 and ADAMTS-12 share the common substrate (COMP)." (PMID 26696755, 2015). "The role of ADAMTS-7 and ADAMTS-12 in the pathogenesis of arthritis was firstly supported by their ability to cleave COMP." (PMID 37651409, 2023). "Overexpression of ADAMTS-7 accelerated the degradation of COMP and the onset and progression of arthritis through formation of a positive feedback loop with TNF-α." (PMID 26696755, 2015). "Overall, ADAMTS-7 metalloproteinases, COMP matrix protein, GEP growth factor, and TNF-α inflammatory cytokine all act in concert to form a key interaction and interplay networks in the pathogenesis of arthritis." (PMID 26696755, 2015). "ADAMTS-7 is a member of ADAMTS family and plays a crucial role in the pathogenesis of arthritis." (PMID 26696755, 2015). "In addition, the cartilage oligomeric matrix protein (COMP)-processing activities of ADAMTS7 and ADAMTS12 were inhibited by α2M, suggesting that dysregulation of the ADAMTS7 and ADAMTS12 protease activity through α2M could be involved in arthritis." (PMID 34268335, 2021).
diabetes mellitus (5 papers, 2020 to 2025). A metabolic disorder characterized by abnormally high blood sugar levels due to diminished production of insulin or insulin resistance/desensitization. "The aim of this study was to investigate the association of ADAMTS-7 levels with diastolic dysfunction and various echocardiographic parameters in patients with type 2 diabetes mellitus." (PMID 39768861, 2024). "In this study, we aimed to investigate the association of ADAMTS-7 levels with diastolic dysfunction and various echocardiographic parameters in patients with type 2 diabetes mellitus." (PMID 39768861, 2024). "Our study is the first one to investigate the role of ADAMTS-7 in diastolic dysfunction in asymptomatic patients with type 2 diabetes mellitus." (PMID 39768861, 2024). "The possible role of ADAMTS-7 in diastolic dysfunction and in the development and progression of heart failure in patients with type 2 diabetes mellitus deserves further investigation." (PMID 39768861, 2024). "Additionally, the effect of diabetes, hypertension and dyslipidemia on ADAMTS7 promoter methylation was assessed in AF patients." (PMID 40565590, 2025). "In the discovery phase of this stratified analysis, 3 known CAD loci reached genome-wide significance: ADAMTS7 in subjects with T2D and 9p21.3 and PHACTR1 in the analysis of subjects without diabetes mellitus." (PMID 33321069, 2020).
coronary atherosclerosis (4 papers, 2015 to 2025). Atherosclerosis of the coronary vasculature. "ADAMTS7 encodes a secreted metalloproteinase recognized as a risk locus for coronary atherosclerosis." (PMID 40900730, 2025). "Results from genome-wide association studies (GWAS) demonstrated that ADAMTS-7 was tightly associated with the development of coronary atherosclerosis in existing coronary atherosclerosis." (PMID 26696755, 2015). "A common SNP near ADAMTS-7 was a common genetic risk factor for coronary atherosclerosis, with a 19% increased risk for carriers." (PMID 26696755, 2015).
Stroke (4 papers, 2017 to 2024). Sudden impairment of blood flow to a part of the brain due to occlusion or rupture of an artery to the brain. "Notably, analysis of 341 DE mRNA associated with stroke (259 upregulated, 82 downregulated) in the IR group revealed upregulation of genes like Ccl2, Cxcl1, C3, Serpine1, Adamts7, Csf3, Ptx3, MMP8, Lif, and Lcn2, and downregulation of Gdf10, Agtr2 and Shank3." (PMID 39170713, 2024). "Our findings suggested the variant G allele of ADAMTS7 rs3825807 may protect against stroke, in harmony with GWA studies which have linked the G allele of with lower CAD risk." (PMID 31460868, 2019). "Patients with IS enrolled in our study were subcategorized according to the Trial of Org 10172 in Acute Stroke Treatment (TOAST) classification t to elucidate if ADAMTS7 variants increased overall risk or were limited to a higher risk of specific stroke subtypes." (PMID 31460868, 2019). "We identified colocalization signals at several established single trait loci such as TCF21, ADAMTS7, and LIPA for CAD, and NGF, FHL5, TSPAN2, and SLC24A3 for stroke." (PMID 31917787, 2020). "First, we compared the level of ADAMTS-7 staining in lesions from patients with cerebrovascular symptoms (transient ischemic attack, stroke, or amaurosis fugax) with patients without symptoms." (PMID 28623250, 2017).
intervertebral disc degeneration (3 papers, 2014 to 2024). "In a static pressure-induced rat model with caudal intervertebral disc degeneration, the mRNA levels of ADAMTS4, ADAMTS5, ADAMTS7, and ADAMTS12 were found to be increased significantly." (PMID 32855969, 2020). "It was reported that the expressions of ADAMTS-7 and ADAMTS-12 in the endplate cells isolated from patients with degenerative disc disease were significantly increased." (PMID 24876675, 2014). "Moreover, in intervertebral disc degenerative (IVD) rat model, the level of ADAMTS-7 was significantly increased in the early phase while the level of ADAMTS-12 was increased in the latter phase." (PMID 24876675, 2014).
ST Elevation Myocardial Infarction (3 papers, 2015 to 2024). A myocardial infarction that produces elevation in the ST segments of the ECG. "In this pilot study, we selected patients with AMI (both ST-elevation myocardial infarction (STEMI) and non-STEMI (NSTEMI)) to detect plasma ADAMTS-7 levels and to explore the association between heart function and plasma ADAMTS-7." (PMID 25885961, 2015).
aortic aneurysm (2 papers, 2020 to 2021). A ruptured aneurysm located in the wall of the proximal portion of the descending aorta proceeding from the arch of the aorta. "Using human tissues from aortic aneurysms (AA), it was shown that ADAMTS7 expression was significantly increased in the AA group compared to controls." (PMID 35053160, 2021). "Results from these studies support the potential link of ADAMTS7 as playing a role in LTBP4 cleavage in aortic aneurysms." (PMID 35053160, 2021). "Human aortic aneurysm induction is related to upregulated ADAMTS-7 and downregulated COMP in the ADAMTS7/COMP pathway." (PMID 32095376, 2020).
carotid atherosclerosis (2 papers, 2019 to 2026). A thickening and loss of elasticity of the walls of carotid arteries that occur with formation of atherosclerotic plaques. "To determine which vascular cell types express ADAMTS7, we interrogated single-cell RNA-seq of human carotid atherosclerosis and found ADAMTS7 expression in smooth muscle cells (SMCs), endothelial cells (ECs), and fibroblasts." (PMID 41609669, 2026).
heart failure (2 papers, 2015 to 2024). Inability of the heart to pump blood at an adequate rate to meet tissue metabolic requirements. "According to the receiver operating characteristic (ROC) curve, using a cutoff value of plasma ADAMTS-7 of 5.69 ng/ml was associated with a specificity of 61.0% and a sensitivity of 87.6% for the diagnosis of heart failure after AMI." (PMID 25885961, 2015). "Logistic regression analysis indicated that the association between ADAMTS-7 and heart failure after AMI was independent from traditional cardiovascular risk factors and other biomarkers (odds ratio = 1.236, 95% confidence interval: 1.023 to 1.378, P = 0.021)." (PMID 25885961, 2015). "According to the ROC curve, using a cut-off value of plasma ADAMTS-7 of 5.69 ng/ml was associated with a specificity of 61.0% and a sensitivity of 87.6% for the diagnosis of heart failure after AMI." (PMID 25885961, 2015). "Results indicated that elevated plasma ADAMTS-7 levels were independently associated with heart failure after AMI (OR = 1.236, 95% CI: 1.023 to 1.378, P = 0.021) as well as age (OR = 1.158, 95% CI: 1.013 to 1.438, P = 0.035) and hsCRP (OR = 1.285, 95% CI: 1.002 to 1.411, P = 0.016)." (PMID 25885961, 2015). "More large-scale studies are necessary to further evaluate the potential mechanisms involving the role of ADAMTS-7 in heart failure." (PMID 39768861, 2024). "Prospective studies with a larger sample size are necessary to assess the possible role of ADAMTS-7 in the development and progression of heart failure." (PMID 39768861, 2024). "According to the ROC curve, a cutoff value of plasma ADAMTS-7 of 5.68 ng/ml resulted in a specificity of 61.0% and a sensitivity of 87.6% for the diagnosis of heart failure after AMI." (PMID 25885961, 2015). "Larger multi-center trials are necessary to determine adequately the role of ADAMTS-7 in heart failure after AMI." (PMID 25885961, 2015). "Logistic regression analysis indicated that the association between ADAMTS-7 and heart failure after AMI was independent of traditional cardiovascular risk factors and other biomarkers." (PMID 25885961, 2015). "Finally, the present study was not designed to provide any mechanistic insights into the roles of ADAMTS-7 in patients with heart failure after AMI." (PMID 25885961, 2015).
Hypertension (2 papers, 2024 to 2025). The presence of chronic increased pressure in the systemic arterial system. "In the current section, the results of the analysis of gene-traditional risk factor interactions for CAD are presented, including interactions between genotypic variants of the ADAMTS7 gene polymorphisms and hypertension, overweight/obesity, male gender, smoking, and lipid metabolism parameters." (PMID 38396951, 2024). "By using linear regression adjusted for bleeding, age, gender, hypertension, DOAC dose and renal function, we found that bleeding was significantly associated with ADAMTS7 promoter demethylation (β −3.125, 95% C.I. −6.208, −0.042, p = 0.047)." (PMID 40565590, 2025).
influenza (2 papers, 2012 to 2017). An acute viral infection of the respiratory tract, occurring in isolated cases, in epidemics, or in pandemics; it is caused by serologically different strains of viruses (influenzaviruses) designated A, B, and C, has a 3-day incubation period, and usually lasts for 3 to 10 days. "ADAMTS7 has also been shown to be upregulated by TNF-α and IL-1β secretion, both of which are activated upon influenza infection." (PMID 22606348, 2012). "However, A549 cells treated with siRNAs targeting ADAMTS7 and DPP3, a gene not predicted to be involved in the NF-κB pathway, resulted in complete abrogation of NF-κB regardless of influenza infection." (PMID 22606348, 2012).
peripheral artery disease (2 papers, 2019 to 2024). "It was also demonstrated, that the rs1994016 variant may predispose to peripheral artery disease by affecting gene expression and increased mRNA levels of ADAMTS7." (PMID 38396951, 2024). "Additionally, studies in the Turkish population showed that AA homozygosity of the rs3825807 and CC of the rs1994016 in patients with peripheral artery disease significantly increases the level of ADAMTS7 mRNA, leading to the disease development." (PMID 38396951, 2024).
type 2 diabetes mellitus (2 papers, 2023 to 2024). A type of diabetes mellitus that is characterized by insulin resistance or desensitization and increased blood glucose levels. "To summarize, the rs3825807 polymorphism of the ADAMTS7 gene could be used as a genetic marker for MI in patients with type 2 diabetes, and the AA genotype might be a genetic risk factor for MI." (PMID 36833435, 2023).
acute coronary syndrome (1 paper, 2024). Signs and symptoms related to acute ischemia of the myocardium secondary to coronary artery disease. "A similar effect was observed in the Chinese population in the case of the rs1994016 polymorphism, where the C allele was associated with an increase in ADAMTS7 concentration and the risk of acute coronary syndrome." (PMID 38396951, 2024).
allergic asthma (1 paper, 2022). A asthma with a basis in a pathological type I hypersensitivity reaction. "Using murine models of allergic asthma, we demonstrate that ADAMTS7 is induced in response to HDM sensitization resulting in Th2 eosinophilic airway inflammation." (PMID 35503474, 2022). "We used an HDM-induced experimental murine model of allergic asthma to investigate whether ADAMTS7 expression in the lung modulates the subsequent induction and development of Th2 immune response to inhaled aeroallergen HDM." (PMID 35503474, 2022).
Arrhythmia (1 paper, 2025). Any cardiac rhythm other than the normal sinus rhythm. "Notably, ADAMTS7 mutations were enriched in very early-onset arrhythmia patients (OR = 9.71 [2.38–47.74], P-value <0.001)." (PMID 40900730, 2025).
asthma (1 paper, 2022). "The present study demonstrates, for what we believe is the first time, a causal role of ADAMTS7 in modulating DC function in the pathogenesis of Th2 immune responses to HDM in experimental allergen-induced asthma." (PMID 35503474, 2022). "In aggregate, we provide compelling evidence that ADAMTS7 plays a pivotal role in allergic airway disease and Th2 immunity and would be an attractive target for asthma." (PMID 35503474, 2022). "Overall, these results showed that ADAMTS7−/− mice have a phenotype of increased eosinophilic airway inflammation, mucous cell metaplasia, and Th2-mediated immune responses in HDM-induced airway inflammation and asthma development." (PMID 35503474, 2022).